VDR (vitamin D receptor)
Diseases named in the same sentence as VDR in open-access papers (continued):
Sharing a sentence is not in itself a finding about the gene and the disease.
tumor (continued). "In CESC patients, VDR expression was positively correlated with neutrophils (Cor=0.229, P=1.18e-04) and dendritic cells (Cor=0.245, P=3.86e-05) and negatively correlated with tumor cell purity, but not with the abundance of B cells, CD8+ T cells, CD4+ T cells, and macrophages." (PMID 39268267, 2024). "Tumor samples with high (>50%) expression and intermediate (10–50%) expression were considered as significant VDR expression, while low (<10%) expression and non-expressing, so-called negative cells were considered as non-significant VDR expression during the later statistical analysis." (PMID 35884356, 2022). "Treatment with calcitriol, indeed, in normal organoids, upregulates stemness-related genes, whereas in tumor organoids it mainly acts on cell proliferation without a significant impact on stemness-related genes expression, by demonstrating the different role of VDR in these two cell subpopulations." (PMID 32560347, 2020). "Additional open questions are whether the levels of VDR, CYP27B1 and CYP24A1 and ROR in the tumor cells can also serve as reliable prognostic factors and in what way the level of VDR may affect the efficiency of vitamin D in inhibiting the tumor growth and aggressiveness." (PMID 31235702, 2019). "However, IHC with 8-oxo-dg to specifically detect DNA damage revealed little change among experimental groups, implying that rather than increasing DNA damage, loss of VDR amplifies β-catenin/TCF signaling, which in turn leads to increased tumor multiplicity/progression in the distal colon." (PMID 27768599, 2016). "The inability of vitamin D3 or VDR to significantly regulate VEGF expression in R7 cells or MMTV-Ron tumors, respectively, suggests that VDR signaling may not play a role in mitigating angiogenesis in this tumor model, but future work is warranted to satisfy this claim." (PMID 26008979, 2015). "This suggests that dietary Vitamin D3, at least in the context of concomitant UVB irradiation, may enhance the oncogenic properties of ΔNp63α by increasing the ratio of ΔNp63α to PTEN, rather than altering its tumor suppressive attributes, namely induction of VDR." (PMID 25191969, 2014). "Moreover, in vivo, mice lacking VDR exhibited enlarged blood vessels to perfuse tumor lesions." (PMID 24084056, 2013). "82% of CHL cases, regardless of the subtype, expressed VDR and in majority of the cases, VDR expression was directly proportional to the quantity of FOXP3 expressing lymphocytes in the tumor microenvironment." (PMID 32513132, 2020). "However, VD3-stimulated upregulation may not be possible in all types of VDR-positive neoplasms." (PMID 30961641, 2019). "Our in vivo experiments indicate that ablation of the VDR in MCF-7 cells strongly reduces tumor formation within the bone environment, since about 87% of the mice failed to develop histologically visible tumors or tumor-related changes in the bone." (PMID 28460457, 2017).
infection (140 papers, 2006 to 2026). The state of being infected such as from the introduction of a foreign agent such as serum, vaccine, antigenic substance or organism. "In most pathologic states (infection, inflammatory disease, etc.), a VDR deficiency is one of many factors contributing to pathogenesis." (PMID 38248835, 2024). "Expression of VDR can appear in the presence of infection and mitogen stimulation, underlining a connection between the VDR signaling pathway and CTL activity." (PMID 36077185, 2022). "Animal studies also revealed out a strong association between VDR and H. pylori infection, with VDR knockdown mice experiencing an increased susceptibility to this infection." (PMID 36292016, 2022). "Tissue-specific deletion of VDR changes the virome and functionally changes viral receptors, which leads to dysbiosis, metabolic dysfunction, and infection risk." (PMID 34375154, 2021). "Searches for polymorphisms of the CARD15 (NOD2), SLC11a1 (NRAMP1), LRRK2, PTPN2/22 and VDR genes have been productive as they reveal susceptibilities for infection by mycobacteria due to impaired pathogen recognition or failure of phagosome maturation." (PMID 32033287, 2020). "These genes regulated by the transcription factor VDR encode for proteins that relate to acute response to infection, general functions in infection and for autoimmune responses." (PMID 32521634, 2020). "The results of several studies have demonstrated that the anti-infection role of VitD3 against M. tuberculosis is closely associated with VitD3/VDR-signal mediated antimicrobial responses and the production of CAMP." (PMID 33194806, 2020). "We especially focused on TNF-α and VDR genes because the elderly are often associated with hospitalization, severe infection, and disability." (PMID 31887189, 2019). "Conversely, VDR KO mice were more susceptible to infections with Listeria monocytogenes, Salmonella and C. rodentium than wildtype (WT) mice." (PMID 30723466, 2019). "Further studies are required to determine how VDR polymorphisms influence susceptibility to infection or to clinical disease development." (PMID 27595605, 2016). "First, to analyze the possible implication of the VDR polymorphisms in the susceptibility to infection by T. cruzi, the allelic and genotypic frequencies of seronegative and seropositive individuals were compared." (PMID 27502545, 2016). "They analyzed recipient VDR polymorphisms and retrospectively evaluated the association with patient outcomes including infection, GVHD, overall survival (OS) and disease free survival (DFS)." (PMID 23778150, 2013). "VDR dysfunction, linked to 25-hydroxyvitamin D deficiency, is thought to cause a decline in innate immune function that increases susceptibility to infections." (PMID 22726649, 2012). "The Ff + ff genotype may carry more f alleles, leading to further alter rations in VDR function, which may affect the body’s immune response to infection." (PMID 40370697, 2025). "For this reason, the VDR gene has been described to have a “pleiotropic” role, and its polymorphism is associated with a wide array of autoimmune disorders and protection against infection." (PMID 39770689, 2024). "Genetic variants, such as single-nucleotide polymorphisms, that affect the gene encoding the VDR can reduce VD activity and have been linked to a variety of diseases, including rheumatoid arthritis, asthma, and susceptibility to tuberculosis and infections with enveloped viruses." (PMID 38138892, 2023). "The contradictory effects of 1,25D vs. VDR deficiency on infection may be a result of differential effects of vitamin D on inflammation vs. clearance." (PMID 30723466, 2019). "Studies in VDR KO mice have demonstrated that intestinal VDRs play an important role in regulating intestinal inflammation, autophagy, the production of AMPs, and the susceptibility to pathogenic infection." (PMID 28066436, 2016). "Furthermore, the ApaI VDR polymorphism has been linked to the pathophysiology of other infections." (PMID 37319132, 2023).
infection (continued). "In addition, VDR is also highly expressed in the small intestine and colon, where it plays a critical role in immunity, host-microbial interactions, and susceptibility to pathogenic infection." (PMID 36091702, 2022). "In summary, our data have demonstrated that conditional VDR knockout causes changes in the abundance and diversity of the virome and functional changes in viral intestinal receptors, which may further induce intestinal dysbiosis and the risk of infection." (PMID 34375154, 2021). "Here, we analyzed whether four single-nucleotide polymorphisms of the VDR gene (rs731236, rs7975232, rs1544410 and rs2228570) are involved in the susceptibility to infection by Trypanosoma cruzi and/or to chronic Chagas cardiomyopathy (CCC) in a Colombian endemic population for this parasite." (PMID 27502545, 2016). "Immunofluorescence results of tissues from patients show that infection leads to elevated VDR expression and promotes apoptosis." (PMID 40396181, 2025). "The role of the VD/VDR-antimicrobial peptide axis in regulating autophagy during infection has been extensively studied." (PMID 40728969, 2025). "Similar to helper T cells, CTLs also express CYP27B1, and local conversion of 25(OH)D into 1,25(OH)2D can stimulate activation of VDR in response to infection and mitogenic stimuli." (PMID 41041128, 2025). "VD receptor (VDR) is a member of the nuclear receptor superfamily, involved in immunoregulation and resistance to infections." (PMID 40728969, 2025). "VDR increased around day 5, plausibly reflecting a compensatory effort to sustain calcium uptake for eggshell calcification under infection-related stress." (PMID 41472116, 2025). "It primarily exerts its effects through interaction with the vitamin D receptor (VDR), facilitating the receptor complex’s migration to the nucleus and modulating the expression of numerous genes related to immune regulation and infection control." (PMID 39600723, 2024). "As the most affected BARs in our infection models, VDR has been reported to involve in Helicobacter pylori and Salmonella Typhimurium infection, promoting innate immunity against bacterial infection." (PMID 39287458, 2024). "The involvement of vitamin D/VDR in anti-inflammatory action has been demonstrated in numerous infections." (PMID 37319132, 2023). "The vitamin D–cathelicidin axis is the most studied and best characterized among the VDR-dependent signaling engaged in infections and autophagosome formation—the latter one playing a critical role in microorganism clearance and infection resolution." (PMID 36901976, 2023). "At site of infection, VDR gene increases local VDR expression and active vitamin D production in innate immune cells, including alveolar macrophages." (PMID 37559014, 2023). "After infection with VDR-overexpressing lentivirus, we also found that the morphology of neurons was more complete than that of untreated explants." (PMID 36497006, 2022). "Using RT-qPCR, we observed that VDR mRNA was significantly downregulated as early as 4 h post infection." (PMID 36146811, 2022). "In cytotoxic T lymphocytes (CTL) as well, VDR is upregulated in case of infection, and CYP27B1 is always expressed; however, the effects of the vitamin on the proliferation, differentiation, and functions of these cells remain unelucidated." (PMID 35408981, 2022). "Across in ovo treatment, the expressions of IL-2, IL-6, IL-10, TGF-β4, TLR-4, 1α-hydroxylase, and VDR were significantly higher at 2 wk post-infection (28 doa) in comparison to their expression levels before coccidiosis infection (14 doa)." (PMID 36230268, 2022). "In mice, infection with an influenza H9N2 virus induced mRNA for the VDR in the lung and 1,25D-treated animals had reduced lung inflammation." (PMID 35893921, 2022).
infection (continued). "Treatment with the HDAC inhibitor TSA showed to reverse HCMV-induced VDR downregulation, and a ChIP assay further confirmed reduced H3K27 acetylation at the VDR promoter region during infection, pointing toward a mechanism of epigenetic repression." (PMID 36146811, 2022). "Mechanistically, HCMV induced vitamin-D resistance by downregulating the vitamin-D receptor (VDR) within hours of lytic infection." (PMID 36146811, 2022). "Sixty minutes after infection, the fluorescence signal of S. aureus was still almost invisible in macrophages, whose VDR protein expression was inhibited." (PMID 35957979, 2022). "In the same way, the ability of five lactic acid bacteria strains to modulate the vitamin D receptor (VDR) pathways and S. enterica enteritidis-induced inflammation and infection was evaluated using murine organoids." (PMID 35010234, 2022). "Immune cells generally take 2–3 days after infection to become activated and maximize their VDR expression." (PMID 35458125, 2022). "From a functional perspective, the significant changes in PRRs and metabolites related to infection suggest the influence of VDR on intestinal virus homeostasis." (PMID 34375154, 2021). "Meanwhile, LPS treatment stimulated the upregulation of CYP27B1 as well, reinforcing the role of VDR in the barrier function and anti-inflammatory and anti-infection pathways." (PMID 33396382, 2020). "Vitamin D and its receptor vitamin D receptor (VDR) exert a critical role in infections due to their remarkable impact on both innate and adaptive immune responses and on the suppression of the inflammatory process." (PMID 33202670, 2020). "For this reason, HepG2 cells were infected with DENV 2, followed by treatment with 10 μM of the five effective VDR agonists (ZD-1, ZD-2, ZD-3, ZD-5, and ZD-6) for 24 h, after which the level of infection was determined by flow cytometry." (PMID 32616772, 2020). "ILC3 numbers in the small intestine of mice deficient for the vitamin D receptor (VDR—KO mice) were shown to be increased, as was IL-22 expression, resulting in enhanced resistance to infection with Citrobacter rodentium." (PMID 32117267, 2020). "VDR signaling activation during infection leads to innate immune signals for the production of antimicrobial peptides (AMPs), such as human cathelicidin AMP (CAMP) and β-defensin 2, which are important in coordinating vitamin D-induced antimicrobial responses." (PMID 32867365, 2020). "It is well known that the binding of 1,25(OH)2D to the VDR enables expression of multitarget genes, which control the monocytes/macrophages function during infection." (PMID 33202670, 2020). "The biological effects of vitamin D and VDR regulate multiple pathophysiological pathways, including immune regulation, anti-inflammation and anti-infection." (PMID 32538430, 2020). "Environmental factors (like diet, sun exposure, pollutions, and infections) regulate the VDR by altering the vitamin D levels." (PMID 31709782, 2019). "infection monocyte toll-like receptors (TLR1–TLR2) gets activated which results in the upregulation of VDR and the vitamin-D-activating enzyme 25-hydroxyvitamin D-1α-hydroxylase." (PMID 31649297, 2019). "The vitamin D receptor pathway genes that are normally up-regulated during infection in zebrafish larvae were down regulated in the tlr2 mutant." (PMID 31747871, 2019). "Another study based on microarray has shown a 3.3 fold downregulation in VDR expression in cells upon infection with M.TB." (PMID 31649297, 2019). "By contrast, at later stages of immune response to infection, more activated T cells express higher levels of VDR and are therefore more sensitive to 1,25(OH)2D3, with the principal response being minimization of T cell activity and chronic inflammation." (PMID 29066221, 2018).
infection (continued). "To investigate the possible splicing genes regulated by H37Rv infection in THP-1 cells, we screened several candidates that are associated with TB infection, such as cytokines, cell receptors (TLRs, VDR), DC-SIGN, and NRAMP." (PMID 29433383, 2018). "The exposition of human monocytes to pathogens, such as M. tuberculosis and others, up-regulates the expression of CYP27B1 and of VDR, thus enhancing both the cell ability to produce 1,25(OH)2D3 in the site of infection and to respond to this metabolite." (PMID 30400332, 2018). "Other studies in mice demonstrated that VDR reduces the response to infection of the intestinal epithelium." (PMID 30400332, 2018). "Evidence has been provided that probiotic treatment can increase vitamin D levels as well as VDR expression and transcriptional activity in the host, and that VDR plays a key role in the protective effects of probiotics against inflammation and infection." (PMID 29562608, 2018). "The decrease of VDR protein expression upon hMPV infection seemed to contradict the increase of VDR mRNA expression." (PMID 29780383, 2018). "VDR expression was significantly down-regulated following infection with shVDR lentiviral vector that efficiently knocked down VDR expression compared with the control vector (shVDR vs shCtrl)." (PMID 29659618, 2018). "The expression of VDR mRNA was greater in mice treated with calcitriol than in untreated mice, the greatest difference being approximately 2.5-fold on 6 days post-infection." (PMID 28114957, 2017). "Our findings are in line with our previously published data demonstrating increased cathelicidin, an indicator of VDR activation, after infection of human bladder biopsies, only when patients were previously supplemented with vitamin D." (PMID 28749951, 2017). "Infection with E. coli CFT073 led to an increase of VDR in the urinary bladder in a time-dependent manner, as visualized by fluorescent immunohistochemistry." (PMID 28749951, 2017). "To explore the underlying mechanisms of our findings, we investigated the kinetics of vitamin D action in the urinary bladder during infection and the induction and cellular localization of VDR in infected mice." (PMID 28749951, 2017). "Vitamin D receptor has long been known to promote immune tolerance in the acquired immune system while providing protective innate mechanisms against pathogen infection." (PMID 28232830, 2017). "Although several investigators reported and suggested that the VDR polymorphism may be of immune-regulatory significance for PTB but it is not clear that the polymorphisms determine susceptibility to the development of clinical disease or susceptibility to infection." (PMID 27595605, 2016). "This was in concordance with a L. major model wherein VDR knockout mice showed resistance to infection." (PMID 26496711, 2015). "Consistent with its role in the innate immune response, both the enzyme that converts vitamin D to its active form (CYP27B1) and its receptor (VDR) are upregulated in response to any of the infections (pattern "All")." (PMID 26586179, 2015). "Elevated 1,25(OH)2D appears to be evidence of a disabled immune system’s attempt to activate the VDR to combat infection." (PMID 25048990, 2014). "This immunopathology suggests transcription of AMPs by an activated VDR, points to the presence of occult infection and provides additional evidence that olmesartan is a VDR agonist." (PMID 25048990, 2014). "Further studies are required to elucidate the mechanism of 1,25(OH)2D3-activated VDR epigenetic mechanism inhibited synthesis of cytokines in MRSA-stimulated infection by restoring the global level of H3K9me3, a histone H3 mark for gene silencing." (PMID 24661536, 2014). "Of course, given their roles in monopoiesis and macrophage activity, VDR stimulation appears to be crucial to the activity of antigen presenting cells and this is felt to be responsible for the role VDR activity seems to play in response to infections." (PMID 23778150, 2013).